CD4 (CD4 molecule)
Diseases named in the same sentence as CD4 in open-access papers (continued):
Sharing a sentence is not in itself a finding about the gene and the disease.
colitis (continued). "Similarly, CD4+ Th9 cells have also shown a dual effect on tumors, presenting anti-tumorigenic effects in most cancers, but able to promote CRC in colitis-associated neoplasm models." (PMID 41425582, 2025). "Furthermore, we observed increased TF expression on infiltrating immune cells and CD4+ T cells in the colons of mice in a T cell-mediated model of colitis." (PMID 39956825, 2025). "Colitis was induced by transplantation of naïve CD4+ T cells in immunodeficient mice." (PMID 39428941, 2025). "Both conventional CD4 + Th17 cells from HLA-B27 transgenic rats and to a lesser extent Th1 could transfer colitis, and Th17 transferred arthritis." (PMID 40938333, 2025). "Here, we utilized a mouse model of DSS-induced colitis mimicking several key features of human IBD to investigate metabolic characteristics of colonic CD4+ and CD8+ T cells, B cells, eosinophils, neutrophils and intestinal epithelial cells during acute and chronic IBD-like disease and remission." (PMID 41007657, 2025). "It would be interesting to explore whether therapeutic asparaginase could be utilized to prevent the induction or severity of colitis or delay the spontaneous development of diabetes in NOD mice mediated by islet-reactive CD4+ and CD8+ T cells." (PMID 40661510, 2025). "Our previous research indicated that BSCFA homeostasis is maintained in Min pigs with strong resistance to colitis, which may promote the expression of CD4+ T cells." (PMID 40342298, 2025). "Indeed, dietary supplementation with butyrylated starch ameliorated CD4+ T cell-induced transfer colitis by enhancing colonic Treg generation." (PMID 40517372, 2025). "To elucidate the influence of Atg7 in CD4+ T cell immune responses of mucosal and colitis development, we generated Atg7 gene CD4+ T cell‐specific knockout mice (Atg7ΔCD4 mice) and examined the role of Atg7 on regulating differentiation of CD4+ T cell during colitis." (PMID 40887825, 2025). "We discovered that in colitis, pro-inflammatory Th1 and Th17 T-cell subsets, marked respectively by double positive CD4+IFN-γ+ and CD4+IL-17+ staining, accumulated in colon, which were dramatically inhibited by infused P5-MSCs cultured in both 2D and 3D environments." (PMID 39897564, 2025). "Similarly, CD4+ T cells showed a significant decrease in mitochondrial size following chronic DSS colitis, which was also resolved during remission." (PMID 41007657, 2025). "Methods and Results: The induction of colitis in immunocompromised mice receiving CD4+CD25− T cells i.p. resulted in a moderate inflammation and was met with limited protective responses following daily subcutaneous administration of MR120 or MR452 for 8 weeks." (PMID 41011197, 2025). "For example, Rag1−/− or Il22−/−Rag1−/− mice received IL‐22‐deficient or wild‐type (WT) CD4+CD45RBhi T cells intraperitoneally, and although all mice developed colitis, the mice fully lacking IL‐22 developed most severe symptoms." (PMID 38363052, 2024). "For CD4+ IL-4+ Th2 cells, the induction of colitis by DSS and treatment with any cADSCs did not cause consistent and obvious changes." (PMID 39176394, 2024). "Moreover, a cellular affinity assay revealed that PD-L1-Fc/Oxi-αCD nanoparticles can obviously bind CD4+ T lymphocytes, macrophages, neutrophils and DCs in the colonic lamina propria of colitis mice." (PMID 38396052, 2024). "NCOR1 is essential for Treg cell-mediated protection in adoptive CD4+ T cell transfer colitis." (PMID 39466314, 2024). "In line with our results in Il10−/−Mdr2−/− mice, colitis severity and CD4+ T-cell infiltration in the inflamed colon of Il10−/− mice was attenuated under the DDC diet, and frequencies of colonic Foxp3+ Treg cells were increased compared with the regular chow diet." (PMID 38839272, 2024). "They additionally report that transfer of IL‐22 knockout (KO), but not IL‐17 KO T cells (CD4+CD45RBlo T and Treg depleted) to Rag1−/− mice reduced weight loss and colitis scores compared with mice who received WT T cells." (PMID 38363052, 2024).
colitis (continued). "Therefore, we investigated the effect of priming with diseased tissue on the capacity of cADSCs to modulate an imbalanced Th-cell paradigm by the phenotypic analysis of CD4+ Th cells from mice with colitis." (PMID 39176394, 2024). "Inhibiting the ubiquitination of TRIM21 and the degradation of IRF3 in colitis induced by TRIM21-/-mice caused an increase in IL-17+CD4+ and IFN-γ+CD4+T cells, accompanied by an intensified immune reaction from CD4+T cells, culminating in heightened inflammation of the intestinal mucosa." (PMID 39165359, 2024). "Specific clustering of intestinal CD4+ cells induced colitis in an adoptive transfer mouse model." (PMID 38918576, 2024). "Similarly to naïve CD4+ T cell–induced colitis, we found that MP cells contribute to pathogenesis of colitis in a manner dependent on type 1 and 3 immune responses." (PMID 39630890, 2024). "To further investigate the contribution of lymphoid cells to the exacerbated colitis phenotype seen in Rasal3−/− and Arhgef2−/− mice, we tested the ability of B6, Rasal3−/− and Arhgef2−/− naïve CD4+ CD25−CD45RBHi T cells to induce colitis upon adaptive transfer into lymphopenic Rag1−/− mice." (PMID 38200184, 2024). "Additionally, CD4+ T cells were likely the primary targets for the immunomodulatory potency of IL-12 signaling during colitis." (PMID 38498592, 2024). "Similarly, polyclonal naïve (CD45RBhi, CD44lo, and/or CD62Lhi) CD4+ T lymphocytes can induce severe colitis and inflammation in other organs when transferred into immunodeficient mice." (PMID 39630890, 2024). "Moreover, they prevent the development of colitis after the adoptive transfer of naïve CD4 T cells into immunodeficient mice." (PMID 39682428, 2024). "Critically, the colitis mice also exhibited an abnormal imbalance of mTh17/mTreg cells with higher frequencies of CD4+CCR7+CCR6+ cmTh17 and CD4+CCR7−CCR6+ emTh17 cells and lower frequencies of CD4+CCR7+Foxp3+ cmTreg and CD4+CCR7−Foxp3+ emTreg cells in the MLNs." (PMID 38202824, 2024). "MiR-21 activates macrophages and naive CD4+ cells to release inflammatory mediators, intensifying colitis, which may indirectly influence the homeostasis of the microbiota." (PMID 39882244, 2024). "In contrast, male and female Rag1tm1Mom mice that received an intraperitoneal injection of splenic CD4+CD45RBhigh T cells from C57BL/6 WT donor mice developed a colitis phenotype, characterized by colonic histopathology and increased expression of inflammatory cytokines in the colon and serum." (PMID 38255320, 2024). "However, caution should be exercised regarding the clinical application of IRF4 activation in IBD, as IRF4 expressed in CD4+ T cells mediates the development of Th17-dependent experimental colitis." (PMID 39403381, 2024). "Additionally, ICB‐induced colitis is characterized by an increased presence of CD4+ effector and Tregs cells, along with enrichment of CD8+ tissue resident memory T (TRM) cells." (PMID 38881673, 2024). "Moreover, conditional knockout of GPR65 in CD4+ T cells reduced Th1 and Th17 cell immune responses in colon mucosa and alleviated intestinal inflammation in murine colitis models." (PMID 39336742, 2024). "In addition, Sf3b1K700Efl/+/Foxp3YFP-Cre Tregs had greatly impaired inhibitory function in vitro in inhibiting T cell activation and in vivo in preventing colitis induced by adoptive transfer of naive CD4+ T cells." (PMID 39303038, 2024). "Therefore, the TCRαβ+CD8αα+ IEL protect immune compromised mice against colitis development following the adoptive transfer of CD4+CD45RBhi T cells." (PMID 38455042, 2024). "CD4+CD45RBhi T cells (naïve) or Treg cell‐depleted CD4+CD45RBlo T cells (memory/effector) derived from WT mice were transferred into Rag1−/− mice to induce colitis." (PMID 38363052, 2024). "In addition, CD4+ IL-17+ Th17 cells tended to decrease in the mice with IFN-γ-primed cAMSCs compared to the DSS-induced colitis mice." (PMID 39595338, 2024).
colitis (continued). "CD4+ T cells from Sf3b1K700Efl/+/Foxp3YFP-Cre mice display defective Treg differentiation and inhibitory function, which is demonstrated by failed prevention of adoptive transfer colitis by Sf3b1K700Efl/+/Foxp3YFP-Cre Tregs." (PMID 39303038, 2024). "Moreover, transplantation of a Treg-enriched population (CD4+CD45RBlo T cells) can sufficiently attenuate the development of colitis." (PMID 39085655, 2024). "Findings from selective depletion of CD4+ and CD8+ T cells or the use of IFNγ‐neutralizing antibodies in ICB‐driven colitis indicated that CD4+ T‐cell‐mediated responses and IFNγ are primarily responsible for the intestinal inflammation caused by CTLA‐4 blockade." (PMID 38881673, 2024). "In addition, ICI‐induced colitis has been reported to be associated with marked CD8+ cell infiltration and a high CD8/CD4 ratio, distinguishing it from other forms of colitis, including ulcerative colitis, Crohn's disease, and ischemic colitis." (PMID 38634742, 2024). "Further studies confirmed that BBR inhibited the TH1/TH17-related JAK/STAT pathway of LP CD4+ T cells and mediated IFN-γ and IL-17A production by LP CD4+ T cells through AMPK activation in vivo experiments with colitis SCID mice and in vitro experiments with LP CD4+ T cells." (PMID 37836654, 2023). "The majority of the CD8+CD103+ T-cells in the inflamed gut of CPI-colitis patients were proliferating, whereas active proliferation of CD4+ T-helper 1 (Th1) cells occurred in the peripheral blood (PB), suggesting local and systemic expansion of different T-cell subsets." (PMID 36776862, 2023). "However, the abundance of DP CD4+CD8+ T cells in colon tissues was markedly decreased in the DSS-induced colitis group compared to the healthy control group." (PMID 37653406, 2023). "In addition, the paper nicely showed that the β-hexosaminidase-specific CD4+ IELs can play a protective role in a mouse model of colitis." (PMID 37901813, 2023). "Similarly, preferential expansion of Tregs via rapamycin prevented colitis development in a CD4 T cell transfer model in mice." (PMID 38107848, 2023). "Depletion of colonic microbiome blocks CD4+ T cell–induced colitis." (PMID 37427591, 2023). "Importantly, TslprKO mice were prone to colitis following adoptive CD4+ T cell transfer and showed heightened expansion of colonic CD4+ T cells in response to immune checkpoint blockade (ICB) therapy." (PMID 37427591, 2023). "In contrast, NK1.1+NKG2D+CD4+ T cells exacerbated the outcome of colitis." (PMID 38139373, 2023). "In addition, CD4+ T cells deficient in PDK4 induce less intestinal inflammation in both DSS-induced colitis and naïve T cell adoptive transfer colitis." (PMID 37809060, 2023). "Corresponding with IFN-γ expression, the frequency of T-bet+ T cells was elevated during DSS colitis, which—especially in CD4+ T cells—could be limited by the late administration of tofacitinib medication." (PMID 37275854, 2023). "In our present study, oral administration of PELNs significantly increased the levels of indole derivatives, effectively decreased the expression of Zbtb7b, and prominently facilitated the differentiation of DP CD4+CD8+ T cells in colonic tissues of mice with DSS-induced colitis." (PMID 37653406, 2023). "Colitis was induced in scid mice via the adaptive transfer of CD4+CD45RBhi T cells." (PMID 38012544, 2023). "Furthermore, patients experiencing ipilimumab-induced colitis showed higher absolute counts of peripheral CD4+ T cells and lower percentages of regulatory T cells at baseline." (PMID 36900420, 2023). "Possible mechanisms by which DCA affects immunity in DSS-induced murine colitis include increasing IL-1β secretion, reducing the number of tuft cells in the mucosa, and activating CD4+ and CD3+ T cells to exaggerate immune responses, consequently worsening intestinal inflammation." (PMID 36819995, 2023). "The colitis symptoms could be alleviated by St6gal1 ablation, resulting in decreased proliferation and activation of CD4+ T‐cells cells." (PMID 37424034, 2023).
colitis (continued). "In contrast, STAT3 activation in CD4+ T cells leads to the prevention of apoptosis of pathogenic CD4+ T cells with the ensuing manifestation of chronic intestinal inflammation, suggesting that STAT3 activation in CD4+ T cells promotes colitis." (PMID 37296943, 2023). "Hence, whilst prominent T-cell (but minimal B-cell) infiltration is a general observation in CPI-colitis, anti-CLTA-4 therapy has been particularly linked to CD4+ T-cell accumulation and anti-PD-1 with CD8+ T-cell infiltrates." (PMID 36776862, 2023). "In our study, we observed that Fp-EVs could increase the ratio of CD4+CD25+FOXP3+ Tregs in the colon of DSS-induced colitis mice." (PMID 37968625, 2023). "To further understand how IL23 might regulate pathogenic effector CD4+ T cells in CPI colitis, we constructed a regulatory network predicted to be activated by IL23 based on downstream gene expression changes in Ifng expressing CD4+ T cells." (PMID 37872166, 2023). "TSLP signaling prevents lethal colitis during homeostatic CD4+ T cell expansion." (PMID 37427591, 2023). "If the expression of miR-150 in CD4+ cells is involved in pathogenesis of colitis, it would be expected that the deletion of miR-150 could prevent the development of colitis in Rap1KO mice." (PMID 39132043, 2023). "To assess whether immortalized cADSCs modulate the Th cell paradigm and balance polarized Th cells, we investigated the phenotype of CD4+ Th cells derived from the spleen of mice with DSS-induced colitis." (PMID 38139314, 2023). "However, IL10R-impaired CD4+ T-cells have deficiencies in IL10-secretion and are less capable of suppressing colitis." (PMID 37654482, 2023). "The ablation of tissue resident memory CD4+ T cells protects from experimental colitis in mice." (PMID 37809060, 2023). "Analysis of cytokines predicted to activate Ifng expressing CD4+ T cells in CPI colitis included IL2 (z score 4.7, P < 1.0 × 10−27), IL7 (z score 3.8, P < 9.8 × 10−19), IL15 (z score 3.4, P < 5.2 × 10−34), IL18 (z-score 2.0, P < 4.0 × 10−25) and IL23A (z-score 2.6, P < 2.1 × 10−31)." (PMID 37872166, 2023). "In accordance, circulating colitogenic CD4 TEM cells have been observed during experimental colitis, indicating that sites other than the intestine may present pathogenic lymphocytes able to maintain chronic inflammation." (PMID 36838425, 2023). "CCL8 is expected to play a pro-inflammatory role, as it induces the migration of CD4+ T cells to the skin in a chronic atopic dermatitis model and the migration of macrophages to the inflamed intestine in a dextran sulfate sodium–induced colitis model." (PMID 37567910, 2023). "Therefore, we aimed to investigate the impact of oral administration of PELNs on the differentiation of DP CD4+CD8+ T cells in mice with colitis." (PMID 37653406, 2023). "Given the importance of CD4+T cells in intestinal inflammation, we sought to investigate whether high level DCA-induced colonic inflammation also involves its effects on CD4+T cells differentiation." (PMID 37789469, 2023). "Mechanistically, PELNs enhanced the growth of Lactobacillus reuteri and increased indole derivatives levels, which led to the downregulation of Zbtb7b expression and subsequently induced the differentiation of double-positive CD4+CD8+T cells (DP CD4+CD8+ T cells) in mice with colitis." (PMID 37653406, 2023). "Notably, recombination activation gene (Rag)-deficient mice develop more severe colitis after transfer of ASC-/- CD4+ T cells versus wildtype, NLRP3-/-, or Caspase1-/- CD4+ T cells." (PMID 37081890, 2023). "Either WT or Ctsw−/− CD4+CD25−CD45RBhi cells were transferred into Rag2−/− mice to induce colitis." (PMID 37436991, 2023). "In both CD4+ and CD8+ T cells, GSEA Hallmark pathway analysis identified significant enrichment of processes such as inflammatory responses, IL2/STAT5 signalling, allograft rejection, TNF signalling and apoptosis in CPI colitis." (PMID 37872166, 2023).
colitis (continued). "T cell transfer colitis model is often used to study the CD4+ T cell functions in the intestine." (PMID 38012544, 2023). "These experiments collectively showcased that the lack of eEF2K resulted in an inflammatory microenvironment, exacerbated inflammation-related diseases, promoted colitis, multiple sclerosis, and arthritis through dysfunctional CD4+ T cells, and increased the secretion of pro-inflammatory cytokines." (PMID 37875468, 2023). "The enhanced regulatory function of Ctsw−/− pTreg cells was further evaluated in a T cell cotransfer colitis model.WT CD4+CD25−CD45RBhi cells were transferred into Rag2−/− mice, together with either WT or Ctsw−/− in vitro–differentiated Foxp3+ (GFP) pTreg cells at a ratio of 10:1." (PMID 37436991, 2023). "In addition, extra-intestinal activation of microbiota-specific CD4+ T cells and the concomitant inhibition of mTOR metabolism can remove CD4+ T memory (TM) cells, thereby preventing colitis." (PMID 37511569, 2023). "WT DCs significantly blunted colonic CD4+ T cell expansion and colitis in Rag1KOTslprKO colon compared with TslprKO DCs (P < 0.0001), indicating that TslprWT DCs are sufficient to protect the host from severe colitis." (PMID 37427591, 2023). "Particularly, the aberrant immune response of CD4+ T cells plays a key role in the disturbances of gut homeostasis, and infiltration of activated CD4+ T cells in the inflamed intestinal mucosa is considered as a characteristic feature of experimental murine colitis and human IBD." (PMID 37957143, 2023). "Importantly, we also determined that the cell isolation protocol we employed significantly depleted CD45RBhi CD4+ T cells in our post-sort inoculum, which is important because the transfer of CD45RBhi CD4+ T cells induces T-cell-mediated colitis." (PMID 38187389, 2023). "However, pDCs stimulated by a gut commensal molecule show anti-inflammatory effects on 2,4,6-trinitrobenzene sulfonic acid (TNBS)-induced Th1-type colitis by driving IL-10 production by CD4+ T cells." (PMID 34997096, 2022). "Taken all together, these findings suggest that mature pathogenic pDCs mainly migrate into the ILFs but not the MLN for antigen presentation to naïve T cells and subsequently drive the subsequent differentiation of Th2 CD4+ T cells in the ILFs, thereby causing OXZ colitis." (PMID 34997096, 2022). "Another study using CD4+CD45RBhi T cell-induced colitis in lymphopenic mice showed that resident non-T cells are induced by Teffs in situ to produce TNFa, which in turn induced colitis." (PMID 36466853, 2022). "Moreover, flow cytometry data showed that the number of CD4+CD69+CD103− TRM cells were correlated with disease activity index in DSS-induced colitis." (PMID 35844584, 2022). "Thus, our findings provide strong evidence that MLN-resident iNKT cells possess the capacity to control the differentiation of Foxp3−CD25+CD4+ T cells during DSS-induced colitis." (PMID 36499642, 2022). "KLH- and PBS-treated mice injected with CD4+CD25− T cells experienced severe colitis." (PMID 36289244, 2022). "As the CD4+ T cells in Rag1−/− recipients originated from a R23FR donor in remission, we next tested whether CD4+ T cells of R23FR mice with colitis could directly promote the killing of IECs." (PMID 35468944, 2022). "TIGIT expression is strongly increased in colonic CD4+ T cells from mice with DSS-induced colitis." (PMID 35844584, 2022). "In this study, we evaluated whether cell percentages of CD4+CD45RA+CCR7+CXCR5+ (CD4+ mTfh) cells changed in experimental colitis." (PMID 35388299, 2022). "Furthermore, VitD3 mediated VDR signaling reduced the severity of DSS colitis and found that it increased the ratio of M2 to M1 macrophages as well as inhibiting the differentiation of CD4+ T-cells into Th1 and Th17 T-helper cell subtypes." (PMID 36569849, 2022).